VILMIR (virus inducible lncRNA modulator of interferon response)
Gene: Long non-coding RNA gene on chromosome 17 (32,062,166 to 32,137,372, forward strand). Ensembl gene ENSG00000277511.
Diseases named in the same sentence as VILMIR in open-access papers:
VILMIR is named in the same sentence as 3 diseases in open-access papers, as found by Europe PMC text mining. Sharing a sentence is not in itself a finding about the gene and the disease. The quoted sentences say what the papers report.
viral infection (2 papers, 2025 to 2026). "We previously identified the human lncRNA VILMIR as a novel ISG during viral infection and found that KD of VILMIR in A549 cells resulted in a suppression of the host transcriptional response to IFN-β treatment and IAV infection." (PMID 41378895, 2026). "As viral infection antagonizes many host response pathways apart from interferon, however, we also identified pathways impacted by VILMIR KD that were unique to H1N1 infection, such as phospholipid metabolism and cell cycle regulation." (PMID 40130878, 2025). "This may mean that VILMIR has a regulatory role within translational control or protein processing, which are important cellular processes during a viral infection, as the host translation is tightly regulated in order to limit viral propagation." (PMID 41378895, 2026). "IFIT2 and IFI44L have previously been identified as ISGs during viral infection, supporting our hypothesis that VILMIR may regulate the host interferon response." (PMID 40130878, 2025).
influenza (1 paper, 2025). An acute viral infection of the respiratory tract, occurring in isolated cases, in epidemics, or in pandemics; it is caused by serologically different strains of viruses (influenzaviruses) designated A, B, and C, has a 3-day incubation period, and usually lasts for 3 to 10 days. "In this study, we identified that a previously uncharacterized lncRNA, virus-inducible lncRNA modulator of interferon response (VILMIR), is upregulated after major respiratory viral infections including influenza, severe acute respiratory syndrome coronavirus 2, and respiratory syncytial virus." (PMID 40130878, 2025).
infection (1 paper, 2025). The state of being infected such as from the introduction of a foreign agent such as serum, vaccine, antigenic substance or organism. "As the immediate neighboring protein-coding genes, RHOT1 and LRRC37B, were not identified in this round of RNA-seq, it seems unlikely that VILMIR regulates these genes during infection." (PMID 40130878, 2025). "Since after suppression of host IFN responses (IAV vs IAVdNS1 infection and pretreatment with ruxolitinib before SARS-CoV-2 infection) there was a significant decrease in STAT1 upregulation as well as VILMIR upregulation, we predicted that VILMIR may be regulated by STAT1." (PMID 40130878, 2025).